ATR (ATR checkpoint kinase)
Diseases named in the same sentence as ATR in open-access papers (continued):
Sharing a sentence is not in itself a finding about the gene and the disease.
tumor (563 papers, 2006 to 2026). "Numerous studies have demonstrated increased dependence on ATR signalling in ARID1A‐deficient tumours, along with synthetic‐lethal sensitivity to ATRis." (PMID 41537447, 2026). "Loss of ATM function enhances tumour dependence on ATR signalling; therefore, ATM mutation or deletion is considered a potential predictive biomarker for ATRis." (PMID 41537447, 2026). "Immunoblotting and IHC analyses confirmed that tumor suppression was associated with reduced Src and ATR activities in the tumors." (PMID 41343245, 2026). "Nuclear ATR negativity was linked with larger tumors and higher histological grade, consistent with a role in tumor progression." (PMID 40869030, 2025). "WES of one eyelid mBCC tumour–stroma pair identified 150 shared nonsynonymous mutations—representing 76.5% of all stromal mutations—including mutations in ATR, EPHA3 and GLI3." (PMID 41373535, 2025). "Combination of radiotherapy (RT) and kinase inhibitors of the DNA damage repair system (DDRi), targeting Ataxia Telangiectasia Mutated (ATM) or ATM and Rad3-related (ATR), are promising, but the consequences on tumor cell phenotype are still scarce." (PMID 40883442, 2025). "Combining IMPDH inhibitors with ataxia telangiectasia mutated and Rad3-related (ATR) inhibitors significantly increased levels of replication stress in vitro and reduced tumor growth in vivo." (PMID 40491496, 2025). "Conversely, HBCx-15 model displayed a high DSB repair deficiency in ATR/HR pathway 4, leading to complete tumour regression with talazoparib monotherapy." (PMID 39875558, 2025). "Ataxia telangiectasia and Rad3-related protein (ATR) inhibitors preferentially target HR-deficient tumor cells." (PMID 40862711, 2025). "Here, using transcriptomic inference from SMARCB1-deficient tumor cells, we nominate the DNA damage repair kinase ATR as a target for rational EZH2 combination epigenetic therapy." (PMID 40794452, 2025). "It is possible that combination of IMPDH and ATR inhibitors would create extensive DNA damage in tumor cells, making them more susceptible to effector functions of immune cells reenergized by immunotherapy." (PMID 40491496, 2025). "FOXP1 haploinsufficiency is identified in development disorders and tumor tissues, these symptoms are similar to that caused by ATR signaling, promoting us to explore the relationship between FOXP1 and ATR signaling." (PMID 39623140, 2025). "Supporting the physiological relevance of this loop, we find pathogenic FOXP1 mutants identified in various tumor tissues with compromised ATR activation and stalled replication fork stability." (PMID 39623140, 2025). "Previous research also shows that tumours in hypoxic environments, where limited oxygen availability hinders DNA replication and repair, are susceptible to ATR inhibition." (PMID 40256842, 2025). "AZD6738, an ATR inhibitor, induces apoptosis, inhibits tumor cell proliferation, and causes double-strand breaks in cHL cell lines." (PMID 40662801, 2025). "The PATRIOT in-human study shows the ATR inhibitor Ceralasertib is tolerated and associates with anti-tumor activity." (PMID 37934611, 2024). "Tumour cells that utilise alternative lengthening of telomeres (ALT) mechanisms to maintain telomere length also appear to be highly susceptible to ATR inhibition." (PMID 38287179, 2024). "There was a significant association between APOBEC3B and ATR expression in the tumor tissues obtained from patients with MIBC." (PMID 38827321, 2024). "In Case 7, SMARCB1 and FANCA variants were detected in the majority of cells (62–92%) in both regions; however, the VAF of an ATR variant (0.28 and 0.13 in Regions A and B, respectively) indicated that this was a later event in the development of this tumour." (PMID 39766052, 2024).
tumor (continued). "Remarkably, the ATMi AZD0156, but not the ATRi AZD6738, robustly restored fork degradation in BRCA- H2AX-deficient cells, indicating that the ATR signalling branch is dispensable for fork protection in these tumours." (PMID 38789420, 2024). "Such DDR deficient tumours rely upon ATR to avoid genomic instability deficiencies and are thus susceptible to ATR inhibition, as a lower threshold of DDR inhibition is needed to induce genomic catastrophe and activation of cell death pathways." (PMID 38227740, 2024). "Inhibition of ATR expression interferes with the response of tumor cells to DNA damage and makes them more susceptible to therapies such as radiotherapy, chemotherapy, and immunotherapy." (PMID 37305685, 2023). "Together, pharmacological inhibitors targeting the components of the ATR/CHK1/WEE1 pathway in 3 tumor entities expressing most KRAS mutations have reached phase II clinical trials." (PMID 36313934, 2023). "This variant did not result in a reduction of ATR expression at mRNA or protein level, but sequencing of the tumor of one of the affected individuals showed a loss of the wild-type ATR allele." (PMID 36749285, 2023). "The inhibition of ATR caused a rise in the level of replication stress, leading to cessation of tumor development." (PMID 37511442, 2023). "Third, in cell line models, loss of specific DNA repair proteins (e.g., XRCC1, ERCC1) causes tumor cell lines more sensitive to ATR inhibition; however, these findings are yet to be implemented in animal models." (PMID 37511442, 2023). "This ATR deficient status correlated with an increased neo antigen expression (including PD-L1) that suppressed the immune response, facilitating tumor growth." (PMID 35563772, 2022). "Tumors with alterations in ATM or ATR (28.9%) displayed co‐occurring copy loss of both genes, with one tumor carrying HD of both genes." (PMID 35229492, 2022). "Previous studies have also demonstrated that ATR inhibitors exhibit strong antitumor activity against HRR-deficient tumor models, such as those that are deficient in BRCA1/2, RAD51, or ATM-mutated." (PMID 34552099, 2021). "As a checkpoint adaptor protein, Claspin directly bridges the ATR/Chk1 pathway, which is the hallmark of tumor progression." (PMID 34071237, 2021). "These 19 de novo variants were present in non-coding regions including those of tumor associated genes ATR, RPS6KA2, IRF3, and CHD3 22–26." (PMID 34011996, 2021). "RT-induced DSBs and subsequent ATM/ATR/CHK1 kinase activities have also been implicated in upregulation of tumor PD-L1 expression through direct STAT1/3-IRF1 activation, independent of neoantigen production." (PMID 34631532, 2021). "In this analysis, ATM and ATR were found to be associated with higher mutational burden (i.e., 50 mutations/tumor) in all samples except one." (PMID 32300177, 2020). "Since ATR is crucial in the intra-S and G2/M phase cell cycle checkpoints, ATR inhibitors cause DNA damage accumulation and cell death by selectively targeting tumor cells with DNA damage-induced G1 cell cycle checkpoints defects." (PMID 32883316, 2020).
tumor (continued). "Inactivating mutations including any in the ATM/Chk2 or ATR/Chk1 pathways potentially would remove the barrier to progression and result in cell proliferation and survival, increasing genomic instability and tumor progression." (PMID 32566745, 2020). "ATR was mutated in 15 tumors and hypermethylated in 1 tumor; together, these tumors were statistically similar to the BRCA-like reference group (p = 0.0035)." (PMID 32997669, 2020). "In an RNAi screen the tumour suppressor gene ARID1A, recurrently mutated in a variety of tumour types, was found to be synthetically lethal in combination with ATR inhibition." (PMID 28448462, 2017). "ATR mutations, as well as copy number alterations, are rare in tumor cells due to the fundamental biological role of this kinase." (PMID 28356161, 2017). "These ATR-inhibitors cause the elimination of certain subsets of tumor cells, but the underlying mechanisms remain poorly defined." (PMID 26755646, 2016). "Considering driver gene, only the SNP rs2227928 in ATR was associated both with risk (OR 1.68, 95 % CI 1.14-2.49 dominant model), tumor size and hormone receptor status." (PMID 26920143, 2016). "ATR-inhibition has recently been demonstrated to induce a selective elimination of certain subsets of tumor cells but the underlying genetic determinants are still insufficiently defined." (PMID 26755646, 2016). "Clinical studies support synthetic‐lethal sensitivity to ATR inhibition in ATM‐deficient tumours." (PMID 41537447, 2026). "Similarly, ATR inhibition potentiates the cytotoxicity of PARP inhibitors in certain BRCA2-mutated tumor cells." (PMID 41373774, 2025). "Patients with an ATR-mutated tumor profile may hypothetically benefit from anti-ATR treatment (berzosertib, ceralasertib)." (PMID 38542259, 2024). "This is likely explainable by the highly heterogenous mutation patterns of different tumor cell lines, some of which could harbor mutations that overrule the synthetically lethal effects between ATR/CHK1 and POLA1." (PMID 39128273, 2024). "One method of measuring ALT-positivity is determining the incidence of ATRX or DAXX mutations, which are prevalent in ALT-positive tumours and therefore may be considered proxy markers of potential sensitivity to ATR inhibition." (PMID 38287179, 2024). "Additionally, a study revealed that ATR inhibition enhances the anti-tumor activity of cisplatin in ATM-deficient tumor cells." (PMID 38807759, 2024). "Our findings hint at a conserved transcriptional core enriched in DNA replication and damage response programs linked to replicative stress, as a potential hallmark of T-cell depleted tumor contextures and point to ATR inhibition as a candidate strategy to effectively revert these conditions." (PMID 38562878, 2024). "The exception to this is RMS335 “OL” which may be due to a mutation in the DNA damage response gene ATR in both the tumor and the tumoroid sample, potentially resulting in the gain of new mutations during culturing." (PMID 35916583, 2022). "We anticipate that susceptibility to ATR inhibitors may also depend on tumor-specific mechanisms of checkpoint adaptation." (PMID 35879366, 2022). "A decrease in the levels of these proteins in experimental cell lines resulted in susceptibility to a class of specific drugs knowns as ATR inhibitors, which may represent a specific vulnerability of these tumor subgroups." (PMID 35740680, 2022).
tumor (continued). "Such tumours may be particularly susceptible to ATR inhibition and may ultimately define populations most likely to benefit from the addition of ATR inhibition to cisplatin or other DNA-damaging agents." (PMID 34040174, 2021). "As shown in other tumor types, inhibitors targeting molecules such as ATR, Wee1 and Chk1, which induce replication-associated DNA damage and potentially cGAS/STING pathway activation through subsequent cytosolic DNA fragments in HNSCC, are promising candidates for combination treatments in HNSCC." (PMID 34204886, 2021). "In addition, we demonstrated in a murine in vivo model that treatment with the ATR inhibitor AZD6738 caused a discernible inhibition of tumor growth rate specifically in tumors harboring the POLD1R689W variant." (PMID 33144657, 2020). "We speculate that even low levels of ATM expression may confer resistance to PARP inhibition, and further investigation to determine whether tumours with low or mutated ATM will be sensitive to olaparib plus or minus an ATR inhibitor." (PMID 31481733, 2019). "Moreover, in the loss of ATM or ATR functions, genome instability such as mutation or deletion will promote cell survival, potentially resulting in cancerous formations and ultimately tumor promotion." (PMID 31772936, 2019). "Patients with tumours characterised by ATM-deficiency may benefit from treatment with a PARP inhibitor in combination with an ATR inhibitor." (PMID 31481733, 2019). "This indicates that ATR-deficient BSFs can enhance orthotopic tumor growth in mice." (PMID 30410668, 2018). "This shows that ATR-deficient BSFs enhance tumor aggressiveness." (PMID 30410668, 2018). "Fang and colleagues showed that ATR+/- mice when crossed into a mismatch repair defective (Mlh1-/-) background (generating ATR+/-/Mlh1-/-) were highly susceptible to embryonic lethality and premature tumour development." (PMID 19440510, 2008). "Moreover, it has been reported that disruption of the ATR gene leads to an increase in the incidence of large benign tumors in heterozygotes, possibly indicating that deficiency in ATR affects the rate of tumor initiation." (PMID 17010193, 2006). "In addition, ATR inhibition plays a significant role in the activation of the immune system by increasing the tumor mutational burden and neoantigen load as well as by triggering the accumulation of cytosolic DNA and subsequently inducing the cGAS-STING pathway and the type I IFN response." (PMID 38474014, 2024). "Additionally, a decreased expression of alpha-thalassemia/mental retardation, X-linked (ATRX), a protein involved in the alternative lengthening of telomeres, is common in OS and has been associated with increased sensitivity to ATR inhibition in other tumor types." (PMID 38730598, 2024).
tumor (continued). "Second, through the analysis of hypomorphic alleles, we have uncovered a hidden function of lin as a tumor suppressor gene that would otherwise be masked by the pleiotropic effect of a strong/null allele, akin to several gene dosage-dependent tumor suppressors such as ATR, HDAC1/2, and Dicer." (PMID 39137945, 2024). "However, the established role of FANCA, SLX4, BRCA2, and ATRX in DNA repair pathways is unlikely to be coincidental, especially considering that we identified mutations in other DNA repair pathway genes, including ATR, which was mutated in two tumours in our study." (PMID 39766052, 2024). "Therefore, it is possible that the concurrent FA/HR aberrations and ATM/ATR mutations help fine-tune the DDR machinery to introduce enough mutations to drive tumorigenesis/tumor progression while keeping certain levels of genomic integrity to maintain tumor cell survival." (PMID 38041093, 2023). "Interestingly, the PARPi-resistant PDE4D7 knockdown cells were substantially susceptible to ATR inhibition, which could provide a potential future therapeutic option for PARPi-resistant tumours." (PMID 37740039, 2023). "In addition, since AIRD1A-mutated tumours exhibited high MSI and tumour mutation burden, the authors speculated that targeted therapy against components of DNA damage response, such as ATR or PARP, could be used in line with ICIs." (PMID 37568604, 2023). "Therefore, we tested whether host immune cell involvement may assist in the rapid tumour loss on ATR inhibition." (PMID 34819497, 2021). "Our POLD1-knockout model thus complements algorithm-based models to predict the pathogenicity of tumor-specific variants of unknown significance and illustrates a novel and potentially clinically relevant therapeutic approach using ATR/CHK1 inhibitors in POLD1-deficient tumors." (PMID 33144657, 2020). "However, ATR expression in CAFs was significantly associated with tumor grade and progression (P = 0.0473 and P = 0.0003, respectively) as well as patient survival (P < 0.0001), while it was inversely correlated with tumor recurrence (P = 0.0017)." (PMID 32414408, 2020). "ARID1A‐mutant tumours, for instance, display heightened sensitivity to inhibition of ATR and several additional targets." (PMID 41537447, 2026). "This process intensifies replication stress and ultimately enhances tumor dependence on ataxia-telangiectasia and Rad3-related (ATR)-dependent checkpoint signaling for survival." (PMID 41993628, 2026). "This work identifies RHNO1 as a key component in the cellular replication stress response and highlights its potential as a therapeutic target for tumor cells reliant on ATR/Chk1 signaling." (PMID 42239230, 2026). "A synergistic combination of checkpoint kinase 1 inhibitor (CHK1i) with low-dose hydroxyurea (LDHU) promotes a unique ATR-independent moderate replication stress response with potent anti-tumour effects." (PMID 41946828, 2026). "Preclinical studies have demonstrated synergistic anti‐tumour effects when ATR or WEE1 inhibitors are combined with ICIs." (PMID 41537447, 2026). "Mechanistically, SMARCA4 loss promotes heterochromatin accumulation and elevates replication stress, rendering tumor cells increasingly dependent on ATR signaling and consequently more vulnerable to ATR inhibitors in vitro and in vivo." (PMID 41514604, 2025). "Compound effectively inhibited ATR signalling pathways, increased DNA damage markers such as γH2AX, and suppressed tumour cell proliferation and migration, as confirmed by colony formation and migration assays." (PMID 40256842, 2025). "Clinically, ATR inhibitors have demonstrated efficacy by differentially targeting tumours with high RS." (PMID 40442403, 2025).